ENSG00000273658
Gene: Miscellaneous RNA gene on chromosome 12 (53,464,720 to 53,464,901, forward strand). Ensembl gene ENSG00000273658.
Homologues: Orthologues: mouse Gm55307 (100% identical).